APOF (apolipoprotein F)
Diseases named in the same sentence as APOF in open-access papers (continued):
Sharing a sentence is not in itself a finding about the gene and the disease.
tumor (9 papers, 2019 to 2026). "Based on these findings, we further investigated the association between DNASE1L3 and APOF expression and tumor grading." (PMID 41602546, 2026). "Low APOF expression is then associated with poor prognosis for various tumor types, but the causal relationship might be the opposite of what we thought, and technical levels might in turn regulate a variety of lipid metabolic processes, including cholesterol accumulation." (PMID 37312170, 2023). "The results indicated that DNASE1L3 and APOF expression significantly correlated with various clinical indicators, such as neoplasm histologic grade, tumor stage, and sample type." (PMID 41602546, 2026). "For PRAD, the mRNA expression of APOF was negatively associated with TMB (R = − 0.09), MSI (R = − 0.10), NEO ((R = − 0.10), tumor ploidy (R = − 0.18), HRD (R = − 0.23) and LOH (R = − 0.12)." (PMID 37312170, 2023). "In terms of tumor heterogeneity, for BRCA, the mRNA expression of APOF was negatively associated with TMB (R = − 0.09), MSI (R = − 0.07), NEO (R = − 0.07), HRD (R = − 0.18) and LOH (R = − 0.18)." (PMID 37312170, 2023). "The pan-cancer Spearman analysis showed that the mRNA expression of APOF was negatively correlated with four tumor stemness indexes (DMPss, DNAss, ENHss, and EREG-METHss) with statistical significance for PRAD and was positively correlated for LIHC." (PMID 37312170, 2023). "For example, TOP2A displaying the most significant upregulation has been identified as a biomarker for HBV-related HCC and APOF with the most significant downregulation is considered a tumor suppressor in HCC." (PMID 33133125, 2020). "We found that ApoF expression was significantly down-regulated in the tumor tissues when compared with the expression level in the adjacent non-tumor tissues." (PMID 31687155, 2019). "Tumor growth, evaluated with tumor volume and weight, was significantly decreased in mice carrying ApoF-overexpressing xenograft as compared with those from the control group (P < 0.001)." (PMID 31687155, 2019). "In conclusion, we identified a cancer-related gene and explored the function of ApoF in tumor biology." (PMID 31687155, 2019). "We also proved that the overexpression of ApoF significantly inhibited the tumor growth in vivo." (PMID 31687155, 2019). "ApoF may serve as a tumor suppressor in HCC and be a potential application for the treatment of this disease." (PMID 31687155, 2019). "Taken together, these results suggest that ApoF may perform the function of a tumor suppressor." (PMID 31687155, 2019). "Six sEV proteins were identified, namely, GCLM, KEL, APOF, CFB, PDE5A, and ATIC, which properly distinguished normal control, early neoplasia, and advanced neoplasia patients from each other." (PMID 34589434, 2021). "APOF is elevated during tumorigenesis in two hormone-dependent tumors, BRCA and PRAD, resulting in elevated circulating cholesterol levels by regulating cholesterol transport and esterification to supply the elevated cholesterol needs of tumor cells." (PMID 37312170, 2023). "The present study identified six sEV proteins, namely, GCLM, KEL, APOF, CFB, PDE5A, and ATIC, that could distinguish early neoplasia, advanced neoplasia, and normal controls from each other well." (PMID 34589434, 2021).
cancer (2 papers, 2019 to 2023). A tumor composed of atypical neoplastic, often pleomorphic cells that invade other tissues. "Multiple immunoregulatory genes as well as immune checkpoint genes were found to be associated with APOF expression levels in all four cancer types." (PMID 37312170, 2023). "Our pan-cancer study offered a relatively comprehensive understanding of the roles of APOF on BRCA, PRAD, KIRP, and LIHC." (PMID 37312170, 2023).
APOF also shares sentences with these, for which no sentence is quoted: Cirrhosis (2 papers); acute respiratory distress syndrome (1); adenocarcinoma (1); adenoma (1); atrial fibrillation (1); cardiovascular disease (1); cholangiocarcinoma (1); dementia (1); endometriosis (1); heart failure (1); hepatitis C (1); hypolipoproteinaemia (1); lung adenocarcinoma (1); mastitis (1); pancreatic adenocarcinoma (1); prediabetes (1); primary biliary cirrhosis (1); Sepsis (1); sphingomyelinase deficiency disease (1); squamous intraepithelial lesion (1); thyroid carcinoma (1); type 2 diabetes (1); typhoid fever (1); viral infections (1).